MYC (MYC proto-oncogene, bHLH transcription factor)
Diseases named in the same sentence as MYC in open-access papers (continued):
Sharing a sentence is not in itself a finding about the gene and the disease.
cancer (continued). "The MYC oncogene is a target gene of the Wnt signaling pathway, which is constitutively activated in the early development of various cancers including CC." (PMID 29525942, 2018). "Parallel-type quadruplexes are found in promoter regions of c-MYC and several other oncogenes that are potential therapeutic targets for cancer including c-KIT, Bcl-2, VEGF, and HIF-1α." (PMID 30312328, 2018). "Mechanistically, the SLIT2/ROBO1 axis exerted cancer-promoting effects on OS via activation of the SRC/ERK/c-MYC/PFKFB2 pathway." (PMID 29523788, 2018). "A team led by Shuibin Lin from Sun Yat-sen University investigated the role of MYC, a gene that is important in other cancers." (PMID 29644114, 2018). "MYC is one of the best-known oncogenes and is currently being considered as a target gene for both the treatment and diagnosis of cancer." (PMID 30499017, 2018). "Observing the same copy number gains as found in the MYCN driven model system (and other MYC driven murine cancer model systems) is a strong indicator of the role of murine chromosome 3 gene dosage contribution to MYCN driven oncogenicity." (PMID 29492199, 2018). "MYC oncogene overexpression/amplification is common in multiple human cancers, in which it regulates proliferation, apoptosis and cell metabolism, among other processes, and its expression associates with poor prognosis." (PMID 29789342, 2018). "Our data suggest that dual inhibition of CDK2 and BET bromodomains can be a novel treatment approach for suppressing MYC-driven cancer." (PMID 29511348, 2018). "It is generally accepted that MYC is one of the key activator of mitochondrial biogenesis in cancer, and opposed effects are exerted by the activation of HIF-1α signaling pathway, as well as FOXO3a." (PMID 29740540, 2018). "MYC-dependent cancer cells can utilize either GLUD or aminotransferases to convert glutamine to α-KG for the TCA cycle." (PMID 28748451, 2018). "It is sure that c-MYC regulates various cancer cellular functions, including cell cycle, cellular survival, proliferation, metabolic reprogramming." (PMID 30053872, 2018). "Recently, it was reported that selective inhibition of either mt-rRNA transcription or mitoribosome function exerts an antiproliferative effect on MYC-overexpressing cancer cells." (PMID 29435159, 2018). "Although numerous studies have successfully targeted these cancers, MYC remains a highly significant therapeutic target." (PMID 29769258, 2018). "We conclude that genes other than MYC are likely regulated by CTCF-bound enhancer-docking sites and that these include multiple cancer-associated genes." (PMID 29641996, 2018). "Cancer cells upregulating MYC are contrariwise protected from untimely death, primarily due to relevant changes in metabolic pathways leading to MYC addiction." (PMID 30619451, 2018). "MYC genes and their transcriptional output have demonstrated to be quite specific targets in cancer." (PMID 29511348, 2018). "MYC has emerged as a clear therapeutic target in other cancers, and many strategies for inhibiting MYC activity through direct or indirect means have been described." (PMID 29463565, 2018). "Recently, deregulated or elevated expression of c-MYC has been reported in many cancers, and sustained activation of c-MYC can inhibit terminal differentiation." (PMID 29700286, 2018). "Previous data demonstrated that overexpression of MYC induces the expression of mitochondrial genes and increases ROS production in cancer cells." (PMID 29789716, 2018). "We demonstrated that T‐025 caused common alternative SEs in cancer cell lines and showed that there was more effective growth inhibition in cancer cell lines with high CLK2 expression or with MYC activation." (PMID 29769258, 2018).
cancer (continued). "Polyamine metabolism is coordinately regulated by MYC to increase polyamines in proliferative tissues, and this is further augmented in the many cancer cells harboring hyperactivated MYC." (PMID 29799508, 2018). "Simonsson and colleagues showed that the treatment of CA46 cells by synthetic 22-mer quadruplex substantially inhibits c-MYC transcription, which underscores the biological and clinical significance of Pu27 motif in cancer therapeutics." (PMID 30239898, 2018). "It is known that cells expressing high MYC levels behave as super-competitors, able to kill and replace less performant adjacent cells; given MYC upregulation in most human cancers, MYC-mediated cell competition is likely to pioneer field cancerisation." (PMID 30619451, 2018). "Capitalizing on this, many mouse models of cancer have been developed using tissue-specific transgenic overexpression of MYC genes, providing insight into the role of MYC in cancer." (PMID 29799508, 2018). "Recent studies suggest that pharmacological targeting BRD4, a member of the BET bromodomain family, can indirectly suppress MYC expression in various cancer models." (PMID 29445162, 2018). "For instance, reported data showed that the over-expression of MYC supports glutamine metabolism in lung tumors, triggering biomass accumulation and cancer cell proliferation." (PMID 30115973, 2018). "In many recent studies, BET proteins have been shown to regulate the expression of several important oncogenes (e.g., MYC) in several types of cancer." (PMID 29796168, 2018). "Protein processing not only features prominently downstream of MYC signaling, but also leads to a MYC dependency in MYC cancers, as supported by multiple lines of evidence." (PMID 29799508, 2018). "In this study we tested if MYC-coordination of rRNA transcription in the nucleolus and in the mitochondrion drives (cancer) cell proliferation." (PMID 29435159, 2018). "Its wide implications in human cancers and the notion that tumors can be dependent on MYC expression (oncogene addiction) make MYC and its network a highly promising target for therapeutic strategies." (PMID 30453475, 2018). "Oncogenic signal transduction from transmembrane receptors along cytoplasmic PI3K-AKT-mTORC1 and RAF-MEK-MAPK serine/threonine kinase cascades down to transcription factors such as MYC is a critical signaling system in many carcinomas." (PMID 29899872, 2018). "Coexpression of MYC and Pim1, on the other hand, leads to formation of carcinomas that exhibit the neuroendocrine phenotype." (PMID 29671777, 2018). "In sum, although MYC has traditionally been regarded to be a pro-apoptotic protein, drug-induced cytotoxicity of KRAS mutant cancer cells appears to depend on MYC inhibition." (PMID 28152508, 2017). "Apart from the expression of its target genes essential for cell cycle progression, c-MYC stimulates cancer growth by re-engineering the metabolic system." (PMID 29169374, 2017). "It is well established that among genes that control normal and cancer cell metabolism, MYC is undoubtedly a pivotal player." (PMID 28362357, 2017). "Expression of the cancer-derived EGFR mutant, commonly known as EGFRvIII, also caused an increase in MYC above background levels." (PMID 28152508, 2017). "The oncogene c-MYC, for example, plays vital roles in cancer cell metabolic adaptation by directly regulating various genes that participate in aerobic glycolysis and glutaminolysis." (PMID 29169374, 2017). "MYC is a common oncogene in many human cancers and MYC–MAX heterodimers bind to E-box sequences in the promoters that binds to genes encoding proteins with a wide range of cellular functions, including metabolism, growth and angiogenesis." (PMID 29166454, 2017).
cancer (continued). "In cooperation with FBXL3 (F-box and leucine rich repeat protein 3), CRY2 binds to MYC phosphorylated at threonine 58 and targets it for degradation, thus restricting proliferation in cancer cells." (PMID 28425940, 2017). "Our lab is currently studying the consequences of intra-tumoural MYC-mediated CC in Drosophila, and our data reveal that this phenomenon is able to shape the final cancer mass in an apoptosis-dependent manner." (PMID 28420161, 2017). "We reveal functional separation between resistance mechanisms and KRAS mutation status and demonstrate that drug-induced cytotoxicity of KRAS mutant cancer cells is contingent on MYC inhibition." (PMID 28152508, 2017). "As revealed by in vivo chromosome engineering, PVT1 is indispensable for MYC-induced cancer promoting effect." (PMID 28930145, 2017). "Owing to the vital oncogenic role of MYC in the metabolism of cancer, we choose MYC as the therapeutic target for future study." (PMID 29084575, 2017). "It is therefore essential to first decipher mechanisms of growth signal-stimulated MYC transcription using in vivo models, with intact signaling environments, to determine exactly how these networks are dysregulated in human cancer." (PMID 28398229, 2017). "A similar pattern is observed with the onco-passengers of other oncogenes (e.g. MYC) and in other cancers as well." (PMID 29069713, 2017). "Critically, SIRT2 is itself upregulated by MYC in cancer cell lines; it constitutes a positive-feedback loop that promotes MYC-dependent transcription and oncogenesis." (PMID 28092669, 2017). "MYC protein stability facilitates uncontrolled induction of cellular proliferation and growth of cancer cells." (PMID 28333115, 2017). "MYC is an oncogenic transcription factor frequently dysregulated in human cancers and is involved in many pathways that support cell oncogenic properties." (PMID 29340052, 2017). "STAT1 has also been shown to act as a driver in cancers, modulating downstream MYC expression, which in turn promotes the capacity for proliferation, migration, and invasion of cells." (PMID 28129744, 2017). "An important role of MYC in this process was previously reported in human cancer cell lines, where MYC inhibits PRODH and promotes the transcription of PYCR1 and ALDH18A1." (PMID 29132502, 2017). "It is pertinent to experimentally establish the effect of the impairment of endogenous MYC on DSB repair pathway(s) in various cultured cancer model systems." (PMID 28590415, 2017). "PVT1 RNA and MYC protein expression correlate in several primary human tumors, and a direct relationship between copy number of PVT1 and MYC copy-increase has been found in more than 98% of human cancers." (PMID 29165379, 2017). "The first evidence for MYC as an immortalizing factor came from a classical RAS co-transformation assay using primary rodent fibroblasts as an in vitro cancer model system." (PMID 28590415, 2017). "Plasmacytoma variant translocation 1 (PVT1), a long intergenic non-coding RNA encoded by the human oncogene PVT1, is located adjacent to the MYC locus on the well-known cancer-related region 8q24." (PMID 29348896, 2017). "Intriguingly, recent findings demonstrated that oncogenic MYC preserves cancer stemness, which enables cancer cells to survive longer with increasing metastatic potential even under genotoxic conditions." (PMID 28590415, 2017). "BRD4 has been reported as target in various cancer types as ovarian, breast, gastric, andregulation of transcriptions factor MYC." (PMID 29077030, 2017). "The c-myc gene, which is translated to the c-MYC protein, is amplified and/or up-regulated in many types of cancer cells, and it plays critical roles in their malignant transformation, proliferation, apoptosis and metastasis." (PMID 28881578, 2017).
cancer (continued). "Altogether, our findings suggest that the innate role of MYC-mediated cell competition in development is conserved in human cancer, with malignant cells using MYC activity to colonise the organ at the expense of less performant neighbours." (PMID 28974715, 2017). "Grandori and colleagues reported that TRIP13 is a c-MYC dependent synthetic lethal gene in c-MYC over-expressed cancer cells." (PMID 28424416, 2017). "Downstream of this so called “gene desert” are two candidate cancer susceptibility genes, the OCT4 pseudogenes POU5F1P1 and c-MYC." (PMID 29232378, 2017). "These in vitro and in vivo observations unfailingly suggest that oncogenic MYC protects cancer-cell genomes from therapeutic DNA-damaging agents." (PMID 28590415, 2017). "PDK1 triggers the phosphorylation of PLK1, which is also upregulated in many cancers, and the latter interacts with MYC, phosphorylates it and results in its accumulation in cancer cells." (PMID 29064423, 2017). "Mechanistically, we showed that MYC, a transcriptional factor involved in many cancers and a well‐known substrate of MAPK/ERK, facilitates IR‐induced DSB repair through regulation of HRR in KRAS‐mutant cells." (PMID 28173629, 2017). "c-MYC was recently shown to be a key regulator of apoptosis ensuing from mitotic defects, sensitizing cancer cells to inhibitors of mitosis by transcriptional upregulation of pro-apoptotic BH3-only proteins as well as suppression of pro-survival Bcl-xL." (PMID 28602975, 2017). "The proto-oncogene MYC is a transcription factor over-expressed in many cancers and required for cell survival." (PMID 29321817, 2017). "As we know, BLC2 (Entrez ID: 4609) and MYC (Entrez ID: 596) are both involved in the pathway of apoptosis and thus influence the development and prognosis of cancer." (PMID 28615526, 2017). "Today, deregulated MYC expression is established as an important driving force in the majority of all human cancers." (PMID 27926480, 2017). "EZH2 proves to be a good therapeutic target in MYC-positive cancers; however, DZNeP lacks the needed specificity to be a promising strategy in clinical applications." (PMID 28505071, 2017). "Since the ET domain is essential for E1A-mediated cellular transformation, our results suggest that MYC and the NuA4 complex function cooperatively in cell transformation and cancer." (PMID 29321817, 2017). "Because focal SCNAs whose sizes were larger than 1 Mbp included an excessive number of genes, we only selected cancer-census genes (MYC and NDRG1) annotated by the COSMIC database from the focal SCNAs (>1 Mbp)." (PMID 28506304, 2017). "While the current study cannot answer this big question in full, we did provide evidence to demonstrate that Menin and MYC are mutually dependent and cooperatively promote cancer progression." (PMID 28474697, 2017). "We also confirmed that MYC, a central point of regulation in cancer metabolism, was significantly up-regulated in LCSCs compared with non-LCSCs." (PMID 28367990, 2017). "Given MYC’s consolidated role in oncogenesis, cell competition is supposed to be relevant to cancer, but its significance in human malignant contexts is largely uncharacterised." (PMID 28974715, 2017). "Another example of connection between 2 functional groups is the association, retrieved by text mining, between MYC and SREBF1 (Cancer and Lipid signaling and cholesterol metabolism, respectively)." (PMID 28962550, 2017). "For instance, eIF2 signaling was among the top canonical pathways both for BPA and BPF; ESR1, MYCN or MYC were found as upstream regulators; and “cancer” as well as “organismal injury and abnormalities” were shared between the three products." (PMID 28628672, 2017). "The MYC gene is also a proto-oncogene: this means that it can trigger cancer if it is continuously overexpressed, which happens in most cancers." (PMID 28598326, 2017). "It has been well known that the oncoprotein c-MYC was overexpressed in a wide range of human cancers." (PMID 29088816, 2017).
cancer (continued). "The oncoprotein MYC plays instrumental roles in development and cancer, strictly dependent on its ability to promote both cell growth and cell death in different genetic backgrounds." (PMID 28420161, 2017). "MYC plays important roles in the pathogenesis of cancer and is particularly important in the survival of cancer cells that are resistant to anti-cancer drugs." (PMID 28696357, 2017). "The MYC oncogenes are key players in cancer initiation and progression, being critical for maintaining the tumorigenic state in numerous cancer types." (PMID 28665315, 2017). "Of note, brief inactivation of MYC is sufficient to induce long-term loss of neoplastic phenotypes, indicating that oncogenic addiction elicited by MYC serves as an “Achilles’ heel” of MYC-expressing cancers." (PMID 28590415, 2017). "Mechanistically, MBZ can modulate the cancer-associated pathways including ELK1/SRF, AP1, STAT1/2, MYC/MAX, although the regulatory outcomes are context-dependent." (PMID 28099902, 2017). "One of the major signaling pathways involved in cancer progression is the MYC/MAX/MAD network, which is related to cell growth, proliferation, differentiation, and apoptosis." (PMID 29383100, 2017). "Beyond cancer, MYC plays an important role in other physiological and pathological processes, namely immunity and immunological diseases." (PMID 28245597, 2017). "CIP2A was previously shown to block PP2A activity leading to enhanced cancer cell signaling such as those mediated by Akt, MYC and E2F1." (PMID 28884018, 2017). "In summary, innovative molecular and cellular approaches are required to target MYC dependence in cancer, and because of its high value as a therapeutic target, these will continue to attract research efforts in the future." (PMID 28362357, 2017). "MYC has a notable role in regulation of glutamine metabolism, and many recent findings elucidating the specific role of MYC in glutaminolytic processes have stimulated broader interest in glutamine as an essential nutrient for cancer cells." (PMID 28443281, 2017). "Lastly, there is a potential role for eventually combining both direct and indirect inhibitors of MYC to develop more novel anti-cancer therapies." (PMID 28362357, 2017). "Genes such as MYC play an important role in pathways relevant for cancer development such as cell-cycle control through Wnt-signaling." (PMID 29110683, 2017). "Here we review recent literature about MYC and cell competition obtained in Drosophila, with a particular emphasis on the relevance of cell death to cell competition and, more generally, to cancer." (PMID 28420161, 2017). "Cancers with gain or amplification in one MYC gene were also likely to have gain in more than one MYC gene (p<0.001) and more than 1/3 of cancers had increased DNA copy number change in at least one MYC gene." (PMID 29240775, 2017). "In light of these reports, oncogenic MYC seems to be an attractive target to overcome chemoresistance in a wide range of human cancers." (PMID 28590415, 2017). "The transcription factor and cell growth regulator MYC is potently oncogenic and estimated to contribute to most cancers." (PMID 28398229, 2017). "Our study provides key mechanistic insights into how sulforaphane inhibits c-MYC activity, thereby exerting its anti-cancer and CSC effects." (PMID 28076844, 2017). "MYC mRNA was expressed at higher levels in HCC samples compared with the matched non-cancer liver tissue." (PMID 28471446, 2017). "We identify MYC as a key component of this process and show that MYC plays an essential cell-intrinsic role in maintaining the survival of KRAS mutant cancer cells." (PMID 28152508, 2017). "Although genotoxic chemotherapeutic drugs effectively kill cancer cells by inducing deleterious DSBs, it is widely recognized that high levels of MYC eventually render cancer cells resistant to genotoxic drugs." (PMID 28590415, 2017).